GRB7 (growth factor receptor bound protein 7)
Diseases named in the same sentence as GRB7 in open-access papers (continued):
Sharing a sentence is not in itself a finding about the gene and the disease.
gastric cancer (continued). "Kaplan-Meier analyses revealed that the high GRB7 expression was significantly relates to a poor survival of gastric cancer patients." (PMID 38129809, 2023). "Subsequently, the upregulation of GRB7 in gastric cancer tissue was confirmed at the protein level through WB analysis." (PMID 38129809, 2023). "GRB7 protein expression levels were positively correlated with the clinical stage of gastric cancer patients, and negatively correlated with the survival prognosis of patients." (PMID 36686796, 2022). "Real-time fluorescent quantitative PCR and Western blot were used to detect the expression of GRB7 in gastric cancer cell lines." (PMID 36686796, 2022). "Multivariate analysis of Cox proportional hazards model showed that the expression of GRB7 was an independent prognostic factor of gastric cancer as well as T classification, N classification, M classification and pathological differentiation." (PMID 36686796, 2022). "GRB7 was significantly higher in 409 cases of gastric cancer than in 37 cases of normal gastric tissue." (PMID 36686796, 2022). "Take together, the expression of GRB7 is up-regulated in gastric cancer cells and gastric cancer tissues." (PMID 36686796, 2022). "Real-time quantitative PCR analysis and Western blot analysis showed that gastric cancer cell lines with high/low expression of GRB7 were successfully established." (PMID 36686796, 2022). "Taken together, GRB7 promotes proliferation of gastric cancer cells through acceleration of G1/S phase cell cycle transition." (PMID 36686796, 2022). "Statistical quantification of mean optical density (MOD) based on different clinical grades of gastric cancer showed that GRB7 protein expression increases with the clinical stage." (PMID 36686796, 2022). "Correlation between GRB7 expression and clinicopathologic characteristics of gastric cancer patients." (PMID 36686796, 2022). "GRB7 can promote the proliferation of gastric cancer cells and is positively related to the self-renewal ability of gastric cancer stem cells." (PMID 36686796, 2022). "Real-time quantitative PCR results revealed that GRB7 levels in the 6 human gastric cancer cell lines were significantly higher than the two normal gastric epithelial cells (NGEC1 and NGEC2)." (PMID 36686796, 2022). "In conclusion, our current research shows that the GRB7 molecules highly expressed in gastric cancer tissues can promote the proliferation of gastric cancer cells and increase the proportion of gastric cancer stem cells." (PMID 36686796, 2022). "We found that the expression of GRB7 in gastric cancer cell lines was higher than that of the corresponding normal gastric epithelial cells, and correspondingly higher in gastric cancer tissues than its paired adjacent tissues." (PMID 36686796, 2022). "Kaplan-Meier curve showed that the prognosis of gastric cancer patients in the GRB7 high expression group was worse." (PMID 36686796, 2022). "The brown color representing GRB7 protein is widely distributed and black in gastric cancer lesions." (PMID 36686796, 2022). "Take together, the expression level of GRB7 protein is positively correlated with the higher clinical grade of gastric cancer and the worse prognosis of patients." (PMID 36686796, 2022). "Western blot analysis showed that GRB7 protein levels were correspondingly increased in 6 human gastric cancer cells." (PMID 36686796, 2022). "Our current research shows that the GRB7 molecule, which is highly expressed in gastric cancer tissues, can promote the G1-S transition of gastric cancer cells." (PMID 36686796, 2022). "In conclusion, we showed that AQP-1 demonstrated oncogenic effects on gastric cancer via GRB7-mediated Ras/ERK activation." (PMID 33209198, 2020). "Frequent amplification of GRB7 and positive changes in expression were also reported in gastric cancer." (PMID 26360582, 2015).
gastric cancer (continued). "In contrast, a positive correlation between an increased number of copies of the GRB7 gene and elevated mRNA expression levels was found in gastric cancers." (PMID 19424485, 2008). "Similarly, the results of this study also indicated that knocking down GRB7 reduced the ability of cell migration in gastric cancer cells." (PMID 38129809, 2023). "In conclusion, the deletion of GRB7 hindered the progression of gastric cancer, indicating that it may be a promising candidate target with potential therapeutic value." (PMID 38129809, 2023). "Therein, we speculated that GRB7 may affect MyD88 expression to regulate gastric cancer progression." (PMID 38129809, 2023). "Taken together, our results showed that GRB7 is increased in gastric cancer and may have an important role in its development." (PMID 38129809, 2023). "Herein, we examined the expression levels of GRB7 in gastric cancer and para-normal tissues, and evaluated the correlation between GRB7 expression and clinicopathologic features, as well as analyzed prognosis of gastric cancer patients." (PMID 38129809, 2023). "Collectively, these results uncovered that GRB7 may become an effective therapeutic target for the treatment of gastric cancer." (PMID 38129809, 2023). "Furthermore, it was discovered that GRB7 regulated malignant cellular characteristics through MyD88 in gastric cancer." (PMID 38129809, 2023). "AQP1 could facilitate proliferation and invasion of gastric cancer cells via GRB7-mediated ERK and Ras activation." (PMID 36803413, 2023). "Together, this study provided evidence that GRB7 may be an effective molecular targets for the treatment of gastric cancer." (PMID 38129809, 2023). "Moreover, the pivotal roles of GRB7 in regulating gastric cancer cell viability, migration and apoptosis were investigated." (PMID 38129809, 2023). "Moreover, GRB7 knockdown inhibited proliferative, migratory abilities, as well as promoted cell apoptosis in gastric cancer cells." (PMID 38129809, 2023). "This study aims to uncover the biological function of GRB7 in gastric cancer process." (PMID 38129809, 2023). "GSEA analysis of GRB7 mRNA levels in gastric cancer tissues and normal gastric epithelial tissues from public databases showed that GRB7 may affect cell proliferation and related processes of intracellular stem cells." (PMID 36686796, 2022). "Taken together, GRB7 is essential for the self-renewal phenotype of gastric cancer cells." (PMID 36686796, 2022). "Furthermore, we established a stable cell line and verified the molecular function of GRB7 in gastric cancer cells." (PMID 36686796, 2022). "Our present study indicates that GRB7 molecules highly expressed in gastric cancer tissues can promote the proliferation of gastric cancer cells and increase the proportion of gastric cancer stem cells, so it is expected to become a potential therapeutic target for gastric cancer." (PMID 36686796, 2022). "In addition, GSEA analysis of GRB7 mRNA levels in gastric cancer tissues and normal gastric epithelial tissues in public databases predicted its possible molecular functions." (PMID 36686796, 2022). "This study shows that GRB7 molecules highly expressed in gastric cancer tissues can promote the proliferation of gastric cancer cells and increase the proportion of gastric cancer stem cells, so it is expected to become a diagnostic molecule or potential therapeutic target for gastric cancer." (PMID 36686796, 2022). "Genomic hybridization analysis using cDNA microarrays detected the co-amplification of the ERBB2 and GRB7 genes in a series of human gastric cancer xenographs, primary tumors and tumor cell lines, although overexpression was apparent for ERBB2 but not for GRB7." (PMID 19424485, 2008). "Together, these results suggest MyD88 may contribute to GRB7-mediated gastric cancer progression." (PMID 38129809, 2023). "Further study suggested that GRB7 silencing could suppress gastric cancer tumor growth in vivo." (PMID 38129809, 2023).
gastric cancer (continued). "In summary, our results suggest that GRB7 may be a valuable therapeutic target for gastric cancer." (PMID 38129809, 2023). "Additionally, it also been reported that GRB7 is amplified in human gastric cancer." (PMID 38129809, 2023). "Thus, we speculated that GRB7 may be used as a predictor prognosis of gastric cancer." (PMID 38129809, 2023). "Results in this study showed that phosphorylation of GRB7 were inhibited by knockdown of AQP-1, suggesting that Aquaporin-1 facilitates proliferation and invasion of gastric cancer cells via GRB7-mediated ERK and Ras activation." (PMID 33209198, 2020). "For example; in gastric cancers the frequently amplified 17q12-q21 region contains genes such as ERBB2, GRB7, JUP, PERLD1, PNMT, PPP1R1B, STARD3, and TOP2A." (PMID 20187983, 2010). "Furthermore, gastric cancer cell lines AGS and MGC-803 were transfected with short hairpin RNAs against GRB7." (PMID 38129809, 2023). "Here, we report for the first time the over-expression of GRB7 mRNA and protein expression levels in gastric cancer and its negative correlation with patient prognosis." (PMID 36686796, 2022). "Further statistical analysis showed that the expression of GRB7 was not related to the patient’s age, but was closely related to the clinical stage and pathological grading of gastric cancer." (PMID 36686796, 2022). "It has been reported that GRB7 is closely related to a variety of human solid tumors, but its role in gastric cancer has not been reported yet." (PMID 36686796, 2022). "However, the expression of GRB7 protein and its function in in human gastric cancer cells have not been reported yet." (PMID 36686796, 2022). "In summary, we speculate that the cytoplasmic GRB7, not the nuclear GRB7, plays a role in promoting the growth of gastric cancer cells." (PMID 36686796, 2022). "Stable gastric cancer cell lines, MTT experiments, clone formation experiments, cell cycle flow cytometry experiments, sphere formation experiments and lateral subpopulation cell sorting experiments were conducted to investigate the role of GRB7 in gastric cancer cells." (PMID 36686796, 2022).
ovarian carcinoma (16 papers, 2012 to 2024). A malignant neoplasm originating from the surface ovarian epithelium. "This work demonstrated that GRB7 is overexpressed in ovarian cancer tissue based on omics data and its overexpression is linked to poor patient outcomes based on TCGA data, consistent with earlier studies on other types of malignancies." (PMID 39204147, 2024). "We explored the possibility that breast and ovarian cancer cell lines also display GRB7 membrane-associated staining." (PMID 32595827, 2020). "GRB7 is a signal transduction molecule and has been implicated in the biology and clinical behaviors of multiple cancers including breast and ovarian cancers." (PMID 32595827, 2020). "Membrane associated GRB7 expression was present in a subset of ovarian cancers with high cytoplasmic GRB7 expression." (PMID 32595827, 2020). "We and others have recently found that GRB7 and its variant, GRB7v, are frequently upregulated in ovarian cancers and are able to enhance cell proliferation, migration/invasion through activating ERK signaling pathway." (PMID 23285101, 2012). "GRB7 has been reported to be implicated in the proliferation of cervical and ovarian cancers, which inspires us to investigate whether the upregulated GRB7 promotes the proliferation of GC cells during H. pylori infection." (PMID 39360313, 2024). "Research has shown that GRB7 protein membrane expression may be associated with a better prognosis in breast and ovarian cancers." (PMID 36686796, 2022). "In this study, we observed an association between GRB7 and angiogenesis in ovarian cancer." (PMID 34783299, 2021). "In conclusion, our study finds that membrane-affiliated expression of GRB7 may be associated with a better prognosis in both breast and ovarian cancers." (PMID 32595827, 2020). "The improved recurrence free survival associated with the GRB7 membrane staining in the ovarian cancer may be due to a better prognosis and/or increased response rate to the systemic therapy such as platinum based chemotherapy." (PMID 32595827, 2020). "GRB7 protein and RNA expression have been associated with high grade ovarian cancers." (PMID 32595827, 2020). "GRB7 expression is also associated with high grade ovarian cancer." (PMID 32595827, 2020). "In conclusion, GRB7 emerges from our study as a potential biomarker for ovarian cancer prognosis and a promising target for therapeutic intervention." (PMID 39204147, 2024). "The colony formation and CCK-8 assays results showed that the proliferation of ovarian cancer cells was significantly reduced upon GRB7 knockout." (PMID 39204147, 2024). "In conclusion, the data suggest that GRB7 has a great deal of potential as a target for improving the effectiveness of immunotherapy for ovarian cancer." (PMID 39204147, 2024). "To investigate the functional effect of GRB7 on ovarian cancer, we knocked out GRB7 in the ovarian cancer cell line OVCAR3 and conducted assays to assess proliferation and migration." (PMID 39204147, 2024). "The results of the transwell and wound healing assays showed that GRB7 knockout reduced the migration of ovarian cancer cells." (PMID 39204147, 2024). "To further verify the predictive power of GRB7 in ovarian cancer overall survival, we conducted univariate and multivariate regression analyses of GRB7 and clinicopathologic factors with OS in OC patients from TCGA and found that it may be an independent risk factor for ovarian cancer." (PMID 39204147, 2024). "Yet, the comprehensive role of GRB7 in ovarian cancer, including its expression patterns, prognostic value, and therapeutic potential, has not been fully elucidated." (PMID 39204147, 2024). "This was also consistent with the results of this study, the expression of GRB7 was significantly increased in ovarian cancer tissues and high expression predicted poor prognosis." (PMID 36642706, 2023).
ovarian carcinoma (continued). "In conclusion, knockdown of GRB7 in ovarian cancer cells is an attractive potential therapeutic target for the suppression of angiogenesis in ovarian cancer." (PMID 34783299, 2021). "A study using clinical samples suggested that the GRB7/extracellular signal-regulated kinases (ERK)/forkhead box M1 (FOXM1) signaling cascade is a promising molecular therapeutic target for ovarian cancer." (PMID 34783299, 2021). "Both mRNA and protein levels of GRB7 are frequently upregulated in ovarian cancer samples compared to normal ovary control samples." (PMID 34783299, 2021). "In vitro experiments have shown that silencing the expression of GRB7 can significantly inhibit the migration and invasion of ovarian cancer cells." (PMID 34783299, 2021). "Multiple studies have found that GRB7 is highly expressed in various tumor tissues, including ovarian cancer tissues." (PMID 34783299, 2021). "Growth factor receptor bound protein 7 (GRB7) plays an important role in regulating the growth and metastasis of ovarian cancer." (PMID 34783299, 2021). "GRB7 is an adapter protein involved in HER2 signaling, and its splice variants have been implicated in ovarian cancer progression." (PMID 33886505, 2021). "Growth factor receptor-bound protein 7 (GRB7), which is a signal transducing adaptor protein that is overexpressed in ovarian cancer, promotes constitutive activation of the MAPK/ERK pathway and thereby leads to enhanced FOXM1 activity." (PMID 34205406, 2021). "This knowledge is essential for development of GRB7 directed therapeutics and understanding of its involvement in breast and ovarian cancer biology." (PMID 32595827, 2020). "Landmark analysis suggested an RFS advantage for ovarian cancers that had GRB7 membrane expression and survived beyond 27 months; GRB7 membrane expression in two or more cores (out of three) predicted an improved RFS." (PMID 32595827, 2020). "Results of past studies of GRB7 expression in ovarian cancer with both RT-PCR and IHC, show that expression of GRB7, and its variant GRB7v, has been associated with high grade ovarian cancer." (PMID 32595827, 2020). "Functionally, Grb7v exhibits a higher oncogenic effect than wild-type Grb7 on the anchorage-independent growth of ovarian cancer." (PMID 31083325, 2019). "GRB7 is overexpressed in ovarian cancer cells and promotes cell proliferation, migration, and invasion in high grade ovarian cancer." (PMID 25644622, 2015). "In this study, by using IHC analysis of ovarian cancer tissue array, we show that GRB7, ERK phosphorylation and FOXM1 are concomitantly increased in ovarian cancer samples." (PMID 23285101, 2012). "In summary, this study shows that aberrant activation of GRB7/ERK/FOXM1 signaling cascade is significantly correlated with the development of ovarian cancer." (PMID 23285101, 2012). "Collectively, these findings confer that GRB7 positively upregulates ERK activity which in turn elevates FOXM1 in ovarian cancer cells." (PMID 23285101, 2012). "To address this gap, we conduct rigorous validation through in vitro experiments and use substantial datasets from TCGA, GTEx, CCLE, and GEO, allowing for a comprehensive examination of GRB7 expression patterns in ovarian cancer and their correlation with prognosis." (PMID 39204147, 2024). "GRB7 may be a promising therapeutic target for ovarian cancer, since our scRNA-seq data analysis showed that it is primarily expressed in malignant ovarian cells." (PMID 39204147, 2024). "Notably, the mRNA levels of GRB7 were significantly higher in ovarian cancer tissues than in normal tissues, as confirmed by TCGA-GTEx and GEO data." (PMID 39204147, 2024). "This suggests that GRB7 may be a viable target for immunomodulatory strategies targeted at enhancing the effectiveness of immunotherapy in ovarian cancer patients, in addition to serving as a possible prognostic biomarker for the disease." (PMID 39204147, 2024).